CRP (C-reactive protein)
Diseases named in the same sentence as CRP in open-access papers (continued):
Sharing a sentence is not in itself a finding about the gene and the disease.
Thrombocytopenia (continued). "Laboratory tests indicated leucocytosis, thrombocytopenia, and elevated C-reactive protein (CRP)." (PMID 39280464, 2024). "On admission, blood tests showed thrombocytopenia (platelet count 50.000/mmc), C-reactive protein (CRP) 10.6 mg/dl, procalcitonin (PCT) 1.05 ng/ml, aspartate aminotransferase 103 U/L, alanine aminotransferase 67 U/L, gamma-glutamyl transferase 173U/L, with normal renal function and coagulation." (PMID 38575935, 2024). "In an SDSE bacteremia study in Japan, an insufficient leukocyte response and thrombocytopenia at admission were linked to poor outcomes, but CRP levels were not predictive at admission, which agrees with our findings." (PMID 39173664, 2024). "The most common laboratory features were high ferritin, thrombocytopenia, and normal CRP." (PMID 39246953, 2024). "Interestingly, the patient presented with some symptoms characteristic of MIS-C, the apparently erroneous top prediction made by the cfRNA model; specifically with severe thrombocytopenia and elevated CRP, which are part of the MIS-C case definition." (PMID 39240972, 2024). "Elevated levels of ferritin, C-reactive protein, and thrombocytopenia were observed in both cases." (PMID 39618590, 2024). "One patient (Case 3) with detailed clinical findings presented with constitutional symptoms including fever of unknown origin, elevated ESR, CRP, and ferritin with mild normocytic anemia and thrombocytopenia." (PMID 39031200, 2024). "The laboratory findings from birth showed mild thrombocytopenia and elevated c-reactive protein." (PMID 37510971, 2023). "In other studies, elevated CRP levels were also positively associated with renal risk factors and diminished filtration or hyperfiltration, but not thrombocytopenia." (PMID 37958881, 2023). "Additionally, in this study, differences in lymphocytes and CRP, LD, and AT levels were observed between patients with thrombocytosis and thrombocytopenia during hospitalization." (PMID 37312072, 2023). "This, together with associations with elevated C-reactive protein (CRP) and thrombocytopenia, suggests that uncontrolled inflammation, high autoantibodies titres and effector T lymphocyte populations may play a pronounced role." (PMID 37556020, 2023). "Laboratory findings from birth showed severe thrombocytopenia and elevated c-reactive protein." (PMID 37510971, 2023). "However, some parameters have been reported as a common finding in cases with worse prognosis (i.e., thrombocytopenia or higher CRP, D-dimer, transferrin, and LDH levels, among others)." (PMID 37623875, 2023). "Patients with these severe clinical complications usually present modified plasmatic levels or alterations in coagulation parameters, thrombocytopenia, increased D-dimer, prolonged prothrombin time, or higher inflammatory protein levels such as C-reactive protein (CRP) and procalcitonin." (PMID 37489362, 2023). "Physiological changes in biochemical indices during pregnancy including thrombocytopenia, increased D-dimer, CRP, and lymphocytosis might explain the differences observed among the groups." (PMID 37384100, 2023). "In addition, the leucocytosis, thrombocytopenia, elevated CRP, and procalcitonin levels were resolved." (PMID 35606754, 2022). "Blood tests demonstrated severe thrombocytopenia, mild leukopenia, and normal CRP." (PMID 36111059, 2022). "Thrombocytopenia, and increased CRP and D-dimer were observed in blood tests." (PMID 36118327, 2022). "The incidence of thrombocytopenia and increased CRP levels detected at the time of diagnosis were significantly higher in the patients with cancer when compared to the subjects with no cancer (18.2% vs. 3.8%, p < 0.001, and 56% vs. 34.1%, p = 0.027, respectively)." (PMID 36326315, 2022).
Thrombocytopenia (continued). "Au and colleagues presented a patient with fever, thrombocytopenia, CRP increase and elevation of several cytokines including interferon-γ, sIL-2R, IL-18, IL-16 and IL-10 after vaccination and ICI therapy compared to cytokine levels before initiation of ICI therapy and vaccination." (PMID 35715501, 2022). "Patients who present with thrombocytopenia, anasarca, fever/elevated C reactive protein (CRP), reticulin fibrosis or renal failure, and organomegaly are defined as iMCD-TAFRO, while those who do not meet these criteria are referred to as iMCD not otherwise specified (iMCD-NOS)." (PMID 36433996, 2022). "The prevalence of complicated appendicitis (CA) (older: 41.2% vs. younger: 14.2%), comorbidities (70.6% vs. 13.2%), and thrombocytopenia (17.7% vs. 4.1%), along with serum C‐reactive protein (CRP) level (6.7 mg/dl vs. 1.0 mg/dl), was significantly higher in older patients." (PMID 35004106, 2022). "For the predicting factor of mortality, the variables with a p-value of less than 0.1 included fever (p = 0.0003), tachycardia (p = 0.0501), tachypnea (p = 0.0377), a positive qSOFA score (p = 0.0049), a cancer history (p = 0.0281), thrombocytopenia (p = 0.0145), and CRP elevation (p = 0.0033)." (PMID 34728700, 2021). "The infant, initially treated for surfactant deficiency, developed worsening hypoxic respiratory failure on the fifth day of life requiring escalating ventilatory support, an elevated level of C-reactive protein, thrombocytopenia, and an elevated level of d-dimer." (PMID 34200043, 2021). "Laboratory tests revealed thrombocytopenia, elevated liver function, and elevated CRP levels." (PMID 33413183, 2021). "In our study population we found thrombocytopenia with raised CRP." (PMID 34508431, 2021). "It has been also reported that C-reactive protein (CRP), procalcitonin (PCT), lactate, and the markers of platelet function (such as thrombocytopenia and impaired platelet aggregation) were associated with the severity and mortality of multiple organ dysfunction." (PMID 34901073, 2021). "Otherwise, V. vulnificus group had significant differences in the clinical characteristics and laboratory data, such as hypotension at emergency room, shorter interval from contact or injury to symptom presentation at ER, presence of bacteremia, thrombocytopenia, and lower CRP level than MRSA group." (PMID 34372768, 2021). "Over the next 5 d, fevers up to 39.8 °C continued, with worsening thrombocytopenia (28 × 109 cells per liter) and increasing inflammatory markers (CRP, 317 mg L−1; LDH, 849 U L−1), including significantly elevated ferritin (6,010 μg L−1 (normal range, 18–464 μg L−1))." (PMID 34040262, 2021). "Similarly, leukocytopenia, neutropenia, thrombocytopenia, low CRP levels, prolonged aPTT, and high CK level were significantly associated with SFTS; however, neither the liver enzymes nor the LDH levels differed between the groups." (PMID 33374620, 2020). "Among the relevant clinical variables, leucopenia, thrombocytopenia, elevated aminotransferases, low C-reactive protein (CRP) and prolonged activated partial thromboplastin time (aPTT), were useful predictive markers for early diagnosis of dengue during the 2007 DENV-1 outbreak in Tainan." (PMID 33170848, 2020). "As a result, concurrent presentation of leukopenia, thrombocytopenia, and normal CRP level may be unusual in patients with prolonged fever and, therefore, associated with differentiated conditions." (PMID 32134948, 2020). "Thrombocytopenia, a raised C-reactive protein level, a low albumin level, and elevated hepatic enzyme levels (particularly AST) were common findings; the latter was shown previously to be useful for differentiating scrub typhus from other causes of undifferentiated fever, such as dengue, in adults." (PMID 30864670, 2020). "Organ dysfunction was associated with elevated admission CRP, elevated WBC, and thrombocytopenia." (PMID 33340348, 2020).
Thrombocytopenia (continued). "Laboratory examination may corroborate the initial suspicion: normal white blood count, mild thrombocytopenia, eosinopenia or aneosinophilia, moderately elevated C-reactive protein (CRP) and lactate-dehydrogenase (LDH)." (PMID 30837820, 2019). "In future practice, it may be useful for clinicians to recognise that a combination of low CRP, thrombocytopenia, neutropenia and leukocytopenia with rash makes DENV a likely clinical diagnosis in the febrile returned traveller." (PMID 30274405, 2018). "DENV-positive results were seen in the febrile returned traveller from SEA, with locally-acquired circulating strains (DENV-1 or -2) and presenting with rash, laboratory features of neutropenia, leukopenia, thrombocytopenia and relatively low CRP for febrile illness." (PMID 30274405, 2018). "By univariable analysis, the factors significantly associated with the occurrence of severe NE were nephrotoxic drug intake, visual disorders, hematuria, leukocyte count >10 × 109 cells/L, C-reactive protein >100 mg/L (>952 nmol/L), and thrombocytopenia <90 × 109/L." (PMID 29774835, 2018). "Similarly, low absolute neutrophil count (ANC) (< 1800/mm3), thrombocytopenia (< 150,000/mm3) and raised C-reactive protein (CRP) (> 10 mg/dl) were seen in 20, 75 and 84% respectively." (PMID 29950162, 2018). "Moreover, we have shown that infusion of pentameric CRP in conjunction with anti-MHC class I antibodies synergistically enhanced TRALI reactions leading to thrombocytopenia." (PMID 27793007, 2016). "Additional mechanisms of action could be that CRP may enhance the PMN respiratory burst as was demonstrated previously in a setting of thrombocytopenia and reactive oxygen species have been suggested to be critical in TRALI induction." (PMID 27793007, 2016). "Infants with necrotizing enterocolitis present with clinical symptoms of abdominal distension, feeding intolerance, bilious vomiting, and bloody stools, and with laboratory derangements characterized by neutropenia, thrombocytopenia, metabolic acidosis, and high C-reactive protein levels." (PMID 26918125, 2015). "However, some cases may show abnormalities such as leucocytosis, thrombocytopenia, neutrophilia, mild pancytopenia, elevated serum amylase and lipase levels, or increased C-reactive protein levels." (PMID 40306103, 2025). "In this cohort of children with a decreased consciousness, the frequent presence of a malarial infection could not be judged from the clinical findings on admission, but the combination of profound aneamia, thrombocytopenia, and a high CRP level increased the odds of a positive malaria test result." (PMID 37087435, 2023). "Moreover, the results reflected that TUG1 gene polymorphism was associated with prolonged disease duration and unfavorable clinical laboratory parameters, such as more arthritis, renal affection, leucopenia and thrombocytopenia, higher CRP, ESR, C3, and C4 levels, and a higher percentage of dsDNA." (PMID 37736902, 2023). "Our prediction tool used 3 variables; leukopenia (WBC count < 4000/mm3), thrombocytopenia (platelet count < 80,000/mm3) and low CRP (< 1 mg/dL), which could be obtained from routine basic laboratory blood tests and are readily applicable in primary care settings." (PMID 30782137, 2019). "High leukocyte counts, thrombocytopenia, high lactate dehydrogenase (LDH), high C-reactive protein (CRP), high procalcitonin, and high interleukin-6 have been associated with severe COVID-19 disease." (PMID 40442623, 2025). "After approximately 48 hours of admission, the patient experienced persistent fever, further elevation in CRP, and worsening rhabdomyolysis, AKI, and thrombocytopenia." (PMID 40636661, 2025). "Six months later, laboratory tests revealed thrombocytopenia (PLT 72.00×109/L), renal insufficiency (CREA 1.44mg/dL), and elevated inflammatory markers C-reactive protein (CRP) 25.28 mg/L, erythrocyte sedimentation rate (ESR) 85 mm/h." (PMID 40248702, 2025).
Thrombocytopenia (continued). "Blood investigations showed a hemoglobin level of 123 gm/L; C-reactive protein (CRP) 69.5 mg/L (normal <5 mg/L); thrombocytopenia (platelet count 40 × 109/L)." (PMID 40948504, 2025). "Labs showed normocytic anemia (hemoglobin 7.6 g/dL), thrombocytopenia (platelet count 78,000/mm3), elevated ESR (89 mm/hr) and CRP (67 mg/L), with normal leukocytes and renal function." (PMID 41552135, 2025). "Laboratory findings included thrombocytopenia, markedly elevated lactate dehydrogenase (LDH), and increased C-reactive protein (CRP)." (PMID 41294908, 2025). "This case presented with relative leukopenia (WBC: 4,400 cells/mm3), thrombocytopenia, normal erythrocyte sedimentation rate (ESR), elevated CRP levels, elevated liver enzyme levels, and hyperferritinemia." (PMID 39119587, 2024). "For example, a diagnostic score consisting of six clinical and laboratory parameters (i.e., high fever, high CRP, high LDH, thrombocytopenia, hyponatremia, and unproductive cough) has demonstrated good diagnostic reliability in several studies." (PMID 39712728, 2024). "Blood tests revealed thrombocytopenia, elevated erythrocyte sedimentation rate (ESR), and anti-streptolysin O (ASO) titer but normal C reactive protein (CRP) and hemoglobin, as well as leukocyte count and formula." (PMID 39201945, 2024). "On admission, leukopenia, thrombocytopenia, increased creatinine and transaminases, LDH, and CRP with a normal ESR were found." (PMID 38892108, 2024). "We report high percentages of typhoid patients who developed leucopenia (9.4%), thrombocytopenia (18.8%), elevated ALT (58.2%), and elevated CRP (99.9%) levels." (PMID 39200066, 2024). "Laboratory workup showed a C-reactive protein (CRP) of 96 mg/L (normal < 5 mg/L), with normal leucocytes of 5,5 × 109/L (normal range 3 to 10,5 × 109/L), and thrombocytopenia of 107 × 109/L (normal range 150 to 450 × 109/L)." (PMID 37996784, 2023). "There was a statistically significant relation confirmed between thrombocytopenia and increased WBC, CRP and lymphocytes (during neonate’s first hours of life) connecting with an ROP diagnosis." (PMID 37835018, 2023). "While kidney failure, thrombocytopenia, raised LDH and CRP levels, and CXR alterations were presented, COVID-19 infection was suspected, and his RT-PCR test was positive." (PMID 37808354, 2023). "Workup for him showed leucopenia, thrombocytopenia, hypoalbumenemia, elevated inflammatory markers (ESR 30, CRP 6.6), high cholesterol level (306 mg/dL), normal renal profile and normal urine analysis." (PMID 37180328, 2023). "Blood tests showed a hyperinflammatory state (ferritin 5,037 μg/L and C-reactive protein 34 mg/L), liver test abnormalities (AST and ALT 2.5 and 3.5 times the upper limit normal (ULN) values, respectively), and thrombocytopenia." (PMID 36225555, 2022). "Laboratory work-up showed raised C-reactive protein (CRP), mild thrombocytopenia, and mildly elevated liver enzymes." (PMID 33748920, 2021). "PLAG significantly decreased plasma levels of the chemokine (C–X–C motif) ligand 1 (CXCL1), CXCL2, interleukin (IL)-6, and C-reactive protein (CRP), which were elevated consistently with the occurrence time of neutropenia, monocytopenia, and thrombocytopenia." (PMID 31752148, 2019). "At the age of 4 months, he had increased levels of erythrocyte sedimentation rate (ESR) and C-reactive protein (CRP) and decreased levels of hemoglobin (Hb) and mean platelet volume (MPV), indicating thrombocytopenia." (PMID 30029636, 2018). "Laboratory results were remarkable for thrombocytopenia (83 G/L on average), elevated creatinine (1.66 mg/dL on average), LDH (759 UL/on average), D-dimers (3062 ng/mL on average), and CRP (19.37 mg/L on average)." (PMID 26451382, 2015). "The most common symptoms included fever, shivers and intensive sweating, thrombocytopenia, elevated creatinine, LDH, D-dimers and CRP, hepatomegaly, and splenomegaly." (PMID 26451382, 2015).
Thrombocytopenia (continued). "The positive predictive value for laboratory-confirmed dengue infection with combination of leukopenia (< 4000/cmm), thrombocytopenia (< 150 × 103/cmm), prolonged aPTT (> 38 sec), elevated aminotransferase (AST/ALT > 1.5) and low CRP (< 20 mg/L) is 93.1%." (PMID 24138072, 2013). "Her blood tests showed a mild elevation in white blood cells (WBCs) compared with her baseline, thrombocytopenia, elevated international normalized ratio (INR), and low albumin, with normal renal function test (RFT), liver function tests, and C-reactive protein (CRP)." (PMID 40041630, 2025). "All surgical patients had elevated CRP and LDH levels, as well as thrombocytopenia." (PMID 41294908, 2025). "There were no cases of thrombocytopenia and no intergroup differences in terms of hemoglobin, folic acid, vitamin B6, vitamin B12 and C-reactive protein (CRP)." (PMID 40722984, 2025). "One patient was found to have intravascular lymphoma on postmortem evaluation while initial presentation showed an elevated CRP level, thrombocytopenia, hyperbilirubinemia, renal insufficiency, and shock without a source of infection." (PMID 40656362, 2025). "For instance, elevated levels of HBP and CRP in conjunction with increased TNF-α and IL-6 can serve as early indicators of severe disease, while thrombocytopenia may signal impending complications such as DIC." (PMID 40963970, 2025). "Inflammatory markers include interleukins (IL) 1b/6/8, C-reactive protein (CRP), ferritin, creatinine kinase (CK), and the neutrophil/lymphocyte ratio (NLR), while coagulation biomarkers include D-dimer, fibrinogen, and platelet count (thrombocytopenia)." (PMID 38500972, 2024). "His initial evaluation in the emergency room showed increased ferritin (15,095 ng/mL), c-reactive protein (CRP) (12.1 mg/dL), erythrocyte sedimentation rate (ESR) (22 mm/h), and AST (63 U/L) with thrombocytopenia (146 K/cu mm), intermittent hypothermia, and hypoxia." (PMID 38577256, 2024). "Blood work revealed a recurrence of severe thrombocytopenia (2x10^9/L) with a still slightly elevated C-reactive protein (3.78 mg/dL), with no other findings worth mentioning." (PMID 38989326, 2024). "For those with typhoid infections, clinical biomarker analysis revealed the presence of leucopenia (65/691, 9.4%), thrombocytopenia (130/691, 18.8%), and elevated alanine aminotransferase (ALT) (402/691, 58.2%) and C-reactive protein (CRP) (690/691, 99.9%) levels." (PMID 39200066, 2024). "Additionally, elevated CRP, ESR, troponin, D-dimer, ferritin, and a tendency towards thrombocytopenia indicate acute inflammation and potential for organ dysfunction." (PMID 39931580, 2024). "Major criteria include anasarca (pleural effusion, ascites, and edema); thrombocytopenia (<100,000/μL, no myelosuppression); and systemic inflammation (fever > 37.5 °C, CRP ≥ 2 mg/dL)." (PMID 38791038, 2024). "Within 6 weeks, she presented with bleeding of the oral mucosa, hemoptysis, melena, severe thrombocytopenia that did not respond to treatment, elevated D-dimer and C-reactive protein levels, severe pain, increased osteolysis, and fractures around the THA." (PMID 37583390, 2023). "Blood results showed leukopenia (5.1 × 10E9/L) and mild thrombocytopenia (117 × 10E9/L), and no blood culture nor CRP (C-reactive protein) was taken because of a lack of material." (PMID 37744436, 2023). "The various stages of infection are characterized by high levels of inflammatory markers such as CRP, interleukins (IL-2, IL-6, IL-7), LDH, ferritin, lymphocytopenia, thrombocytopenia, leukopenia, elevated procalcitonin, D-dimer, prothrombin, fibrinogen, and others." (PMID 36982882, 2023). "Previous clinical studies, however, showed that the titer of anti-HPA-1a antibodies was not strictly correlated with fetal thrombocytopenia, indicating that other confounding factors such as antibody fucosylation and CRP play also important role." (PMID 38077345, 2023).